LUCAT1 (lung cancer associated transcript 1)
Diseases named in the same sentence as LUCAT1 in open-access papers (continued):
Sharing a sentence is not in itself a finding about the gene and the disease.
tumor (58 papers, 2017 to 2025). "Our analysis showed that LUCAT1 expression was positively associated with CSC markers in BC, and the LUCAT1-correlated genes enriched in key tumor signaling pathways." (PMID 40025525, 2025). "Functionally, it promotes tumor cell proliferation and migration by targeting miR-141-3p, identifying LUCAT1 as a promising diagnostic and prognostic biomarker in CHOL." (PMID 40713875, 2025). "Higher exosomal LUCAT1 expression was consistently associated with shorter overall survival, larger tumor size, positive lymph node metastasis, and advanced stages." (PMID 39789501, 2025). "ROC analysis demonstrated the significant diagnostic capability of LUCAT1 in distinguishing CHOL tumor tissues from normal tissues, with an AUC of 0.908 (p < 0.001)." (PMID 40713875, 2025). "First, lncRNAs can serve as diagnostic markers, they can be used for tumour type differentiation and tumour staging (LUCAT1, MALAT1), and their expression can be related to tumour size or be an early marker of its development (MALAT1)." (PMID 38203731, 2023). "In this study, we aimed to characterize the biological role of long noncoding RNA lung cancer‐associated transcript 1 (lncRNA LUCAT1), a novel tumor‐associated lncRNA, in human PDAC." (PMID 31789465, 2020). "In this study, we found that the expression of LUCAT1 was significantly up-regulated in NSCLC tissues compared to non-tumor tissues, and its expression was associated with tumor size, tumor–node–metastasis (TNM) stage and overall survival (OS)." (PMID 28423699, 2017). "According to the collected clinical information, there was a statistically significant association between increased LUCAT1 levels and larger tumor size, and advanced TNM stage." (PMID 28423699, 2017). "In summary, our results provide strong evidence that Lucat1 is up-regulated in ccRCC tumor tissues and cell lines, and is associated with poor prognosis in ccRCC patients." (PMID 29371934, 2017). "In addition, higher CASC9 and LUCAT1 levels are associated with tumor recurrence and the more aggressive properties of HCC cells." (PMID 38398157, 2024). "In addition, high LUCAT1 levels have been associated with late-stage tumour metastasis to the LNs and large tumour volumes." (PMID 38203731, 2023). "Moreover, we found that high LUCAT1 expression was linked to higher tumor recurrence rates and histological characteristics of poorer differentiation." (PMID 37945918, 2023). "High levels of LUCAT1 in tumours are associated with poor OS." (PMID 38203731, 2023). "Moreover, high LUCAT1 levels were associated with late staging in tumor–lymph node metastasis and higher tumor volume." (PMID 37370745, 2023). "In association with clinical presentations, LUCAT1 was effective in distinguishing between normal and tumor tissues (AUC = 0.768) and was correlated with poor prognosis (HR = 1.368, p < 0.05), suggesting the potential of LUCAT1 as a diagnostic and prognostic marker for HNC." (PMID 36980216, 2023). "Notably, increased lncRNA LUCAT1 expression was linked to some clinicopathological characteristics, including larger tumor size and lymphatic invasion." (PMID 31789465, 2020). "Additionally, we found that increased lncRNA LUCAT1 expression was linked to larger tumor size and lymphatic invasion." (PMID 31789465, 2020). "The further loss‐of‐function experiments confirmed LUCAT1 as a tumor promoter in CM." (PMID 31968402, 2020). "In our case, around 50% of patients presented upregulated LUCAT1 and an advanced tumor stage, suggesting that it could be implicated in some mechanisms leading to the progression of PTC." (PMID 31591432, 2019). "Notably, high expression of LUCAT1 was associated with worse tumor regression grades (TRG)." (PMID 31964396, 2020). "We observed that elevated LUCAT1 expression was strongly associated with poor CHOL prognosis Moreover, the tumor size, CA-19-9, and TNM-T-Stage were significantly correlated with the LUCAT1 expression." (PMID 40713875, 2025).
tumor (continued). "In vivo, tumor xenograft experiments confirmed that overexpression of LUCAT1 conferred resistance to osimertinib." (PMID 41145422, 2025). "Tumor size, CA-19-9 levels, and TNM-T stage were significantly associated with LUCAT1 expression (p = 0.034 for tumor size, p < 0.001 for CA-19-9, p = 0.012 for TNM-T stage), suggesting their involvement in CHOL progression." (PMID 40713875, 2025). "The results indicated that the combination of glumetinib and osimertinib suppressed tumor growth more strongly than the monotherapy in LUCAT1-induced resistant cells." (PMID 41145422, 2025). "LUCAT1 expression was assessed in paired tumor and normal specimens using RT-qPCR, revealing significant upregulation in CHOL tumor tissues (p < 0.001)." (PMID 40713875, 2025). "Knockdown and overexpression of LUCAT1 decreased and increased the number and size of tumor spheres, respectively." (PMID 40025525, 2025). "Tumour growth in LUCAT1-enriched exosomes treatment group was faster than that of control groups, and chemoresistance in LUCAT1-enriched exosomes treatment group was enhanced compared with control groups." (PMID 40025525, 2025). "Collectively, our findings highlight that LUCAT1 an effective tumour biomarker, with promising clinical implications as a therapeutic and diagnostic target of BC." (PMID 40025525, 2025). "The results demonstrated that knockdown of LUCAT1 led to the downregulation of multiple key tumor regulatory genes, including HMGA1." (PMID 40025525, 2025). "We found the proportion of LUCAT1 down-regulated cells was decreased in tumor xenografts of GEM-treatment group." (PMID 40025525, 2025). "The tumour weight of LUCAT1-enriched exosomes treatment group was greater than which of control groups." (PMID 40025525, 2025). "Silencing of tumor suppressors via methylation contributes to carcinogenesis, and LUCAT1 can impact this process by virtue of regulating DNA methyl transferase 1 (DNMT1)." (PMID 39594666, 2024). "We also found that DSTN exhibited stronger associations with pathways such as hsa-miR-181c-5p/LUCAT1, IGFL2-AS1, and hsa-miR-23b-5p, suggesting its significant role in tumor regulation." (PMID 39896807, 2024). "To further explore the potential role of LUCAT1, we conducted separate analyses of the functions of LUCAT1+ and LUCAT1− monocytes in tumor tissues." (PMID 38711918, 2024). "High expression of LUCAT1 in LUAD patient tissues was associated with enhanced Lymph Node Metastasis (LNM), advanced Tumor Node Metastasis (TNM) stage and poorer clinical outcome in LUAD patients." (PMID 35646922, 2022). "In this study, we aimed to investigate the biological function and mechanism of lncRNA LUCAT1 in regulating tumor migration and glycolysis of LUAD." (PMID 35646922, 2022). "It indicated that LUCAT1 was an oncogene that promoted the occurrence and development of tumors by affecting metabolic pathways in the tumor microenvironment and inhibiting the immune response of immune cells, resulting in a lousy prognosis." (PMID 36401283, 2022). "Further evidence confirmed that LUCAT1 participated in the regulation of multiple processes of tumor occurrence and development, while the detailed role of LUCAT1 in LUAD metastasis and glycolysis was not well known." (PMID 35646922, 2022). "PVT1, LUCAT1, and LINC00982 thus represent potential diagnostic biomarkers capable of distinguishing between tumor and non‐tumor tissue with high sensitivity and specificity." (PMID 35441392, 2022). "Functional experiments, including wound-healing, transwell invasion assays, glucose absorption, lactate metabolism and tumor xenograft experiments were conducted to identify the biological functions of LUCAT1 in LUAD." (PMID 35646922, 2022). "Increased expression of LUCAT1 induces tumor cell growth and development by regulating the AKT/GSK3β signaling pathway." (PMID 36483915, 2022).
tumor (continued). "RT-qPCR results showed that LUCAT1 was significantly higher in tumours of the scramble group than the shLUCAT1 group." (PMID 32922538, 2020). "Co-transfection of pc-LUCAT1 with miR-181a-5p mimic (miR-181a-5p + pc-LUCAT1 group) neutralized the tumor-promoting effects of pc-LUCAT1 (p < 0.05)." (PMID 32998707, 2020). "To further evaluate the effects of lncRNA LUCAT1 in vivo, we constructed tumor xenograft models by subcutaneous inoculation of sh‐lncRNA#1‐treated PANC‐1 cells in the flanks of the nude mice." (PMID 31789465, 2020). "Tumorous tissues were classified into two groups, high lncRNA LUCAT1 expression group and low lncRNA LUCAT1 expression group, according to the median value of its expression levels." (PMID 31789465, 2020). "ELF1 has been implicated in transcription regulation of several tumor-promoting genes including Tie2, MEIS1, CCL2, LUCAT1." (PMID 32795319, 2020). "VitD can reduce the expression of the tumour-promoting factor LUCAT1 and inhibit the proliferation of OSCC." (PMID 32922538, 2020). "There was a statistically significant difference in the expression of LUCAT1 between different tumour sizes." (PMID 32922538, 2020). "The results showed that tumor volume and weight were increased in the LUCAT1-overexpressing group compared to the control group." (PMID 31964396, 2020). "The tumor volume of mice in pc-LUCAT1 + miR-181a-5p mimic group was significantly smaller than that in the pc-LUCAT1 group (P < 0.05)." (PMID 32998707, 2020). "LUCAT1 expression was significantly increased in ESCC tissues compared with adjacent non-tumor tissues." (PMID 32005028, 2020). "In summary, we demonstrated that the LUCAT1/miR-181a-5p axis constitutes an important regulatory mechanism in BC, whereby LUCAT1 is a tumor inducer and miR-181a-5p is a tumor suppressor." (PMID 32998707, 2020). "Multivariate analysis suggested that tumor grade and LUCAT1 expression level were independent prognostic factors of TNBC." (PMID 31399501, 2019). "The highest fold-change was obtained for lung cancer associated transcript 1 LUCAT1, and thus, this study determines the expression and biological implication of lncRNA LUCAT1 through different in vitro and ex vivo approaches in this tumor." (PMID 31591432, 2019). "e TCF7L2 expression were detected in tumor tissues formed from LUCAT1-silencing or NC-silencing MCF-7 CSCs by IHC." (PMID 31300015, 2019). "In the present study, we found that LUCAT1 was up‐regulated in tumour tissues compared to adjacent non‐cancerous tissues and correlated with tumour size, metastasis and Edmondson grade of HCC." (PMID 30588744, 2019). "Downregulation of LUCAT1 has been linked to lower protein levels of DNMT1 and subsequent reduction of repressive methylation marks in known downstream tumor-suppressor genes under the control of DNMT1." (PMID 31658672, 2019). "The staining of formalin‐fixed paraffin‐embedded (FFPE) subcutaneous tumour tissues with proliferating cell nuclear antigen (PCNA) confirmed the lower proliferation status of LUCAT1 knockdown cells." (PMID 30588744, 2019). "Other examples of lncRNAs that are secreted from tumor exosomes include LUCAT1 and PVT1 in exosomes of liver cancer." (PMID 31658672, 2019). "This study found LUCAT1 expression was related to tumor size (p = 0.015), lymph node metastasis (p = 0.002) and TNM staging (p < 0.001)." (PMID 31300015, 2019). "The t-test of Levene’s test revealed that the average age of onset of tumor was 17,35 years more for patients with low LUCAT1 expression versus those with LUCAT1 overexpression (IC95% 10,18; 24,52) in a significant manner (p < 0.001)." (PMID 31591432, 2019). "There was a significant correlation between LUCAT1 expression and tumor size (p = 0.015), lymph node metastasis (p = 0.002) and TNM staging (p < 0.001)." (PMID 31300015, 2019). "Our investigation exhibited that LUCAT1 expression was prominently increased in TNBC tissues compared to matched non-tumor tissues." (PMID 31399501, 2019).
tumor (continued). "Both LUCAT1 and CASC9 were secreted in exosomes, and higher circulating CASC9 levels were associated with tumor size and HCC recurrence after surgery, suggesting its potential usage as putative non-invasive prognostic biomarker of recurrence." (PMID 30416681, 2018). "We found that tumor growth in the sh-LUCAT1 group was measurably slower than that in the empty vector group." (PMID 28423699, 2017). "Up to 49 days, there was a dramatic decrease in tumor volume and weight in the sh-Lucat1 group compared with sh-LacZ group." (PMID 29371934, 2017). "We found significantly elevated expression of EZH2, Lucat1 and a lower expression of p57 in the tumor samples." (PMID 29371934, 2017). "We divided the patients into two groups on the basis of the median expression for LUCAT1 in tumor tissues: LUCAT1-high group (above the median, n = 34) and LUCAT1-low group (below the median, n = 34)." (PMID 28423699, 2017). "Furthermore, a tumour initiation assay was performed to further evaluate the tumorigenicity capacity of BC cells in vivo, and knockdown of LUCAT1 in BC cells decreased the size, weight and incidence of xenografts." (PMID 40025525, 2025). "Notably, emerging evidence has demonstrated that LUCAT1 plays crucial roles in both embryonic stem cell differentiation and tumor progression." (PMID 40025525, 2025). "The ROC results showed that LUCAT1 could distinguish tumor tissue from normal tissue in CHOL patients." (PMID 40713875, 2025). "Our findings confirmed that LUCAT1 expression is significantly upregulated in CHOL tumor tissues." (PMID 40713875, 2025). "Moreover, metabolic pathway analysis revealed that LUCAT1+ monocytes exhibit lower communication activity in the tumor microenvironment and heightened activity in metabolic functions like glycosaminoglycan degradation." (PMID 38711918, 2024). "Functionally, LUCAT1 directly targeted HIF1α, facilitating tumor growth, which could be reversed by CRISPR–Cas9-mediated depletion of LUCAT1." (PMID 39119602, 2024). "Therefore, LUCAT1 can be considered a tumour-promoting lncRNA with complex intra- and extracellular activity." (PMID 38203731, 2023). "The expression of LUCAT1 in LC samples is related to the tumour size, TNM stage, and OS." (PMID 38203731, 2023). "Thus, MALAT1, LUCAT1, and TUG1 are associated with the survival of patients with LC; HOTAIR can serve as a biomarker of tumour progression; and NEAT1 is related to poor prognosis." (PMID 38203731, 2023). "LUCAT1 was significantly up-regulated in LUAD tumors than in non-tumor tissues." (PMID 35646922, 2022). "LUCAT1 in vitro over-expression brings about rapid tumor proliferation and invasiveness." (PMID 36076273, 2022). "Interestingly, the expression levels of exosomal LUCAT1 remained unchanged upon RNase A treatment, which fully proved its sufficient suitability as tumor markers for LUAD diagnosis." (PMID 35646922, 2022). "In addition, the in vivo experiments further demonstrated that depletion of LUCAT1 hindered tumor growth in vivo, evidenced by resultantly reduced tumor volume and weight." (PMID 31968402, 2020). "Tumor xenograft in vivo assays displayed that lncRNA LUCAT1 inhibited tumorigenecity of PDAC cells." (PMID 31789465, 2020). "Down-regulation of MYC was also observed in LUCAT1-KO tumor tissue by IHC staining than NC group." (PMID 33097685, 2020). "In summary, LUCAT1 is induced by hypoxia and confers chemoresistance to tumor cells." (PMID 31964396, 2020). "Moreover, we observed that the expression of LUCAT1 was significantly upregulated in OSCC tissues compared to non-tumour tissues." (PMID 32922538, 2020). "The role of LUCAT1 in OSCC growth was further confirmed by mouse xenograft tumor model." (PMID 32922538, 2020). "It was shown that overexpression of LUCAT1 could promote the growth of mice tumors, whereas overexpression of miR-181a-5p could attenuate tumor growth." (PMID 32998707, 2020).
tumor (continued). "The results revealed lung colonization in the LUCAT1 overexpressed group with eight mice presenting lung colonization at the end of the experiment, whereas only three mice established lung colonization in the control group, with fewer and smaller tumours." (PMID 30588744, 2019). "The effect of LUCAT1 on increasing tumor size and weight could be inhibited by miR-5582-3p, while the effect of miR-5582-3p on decreasing tumor size and weight could be rescued when LUCAT1 was overexpressed in the nude mouse model." (PMID 31300015, 2019). "Our results indicated that LUCAT1 promotes tumour progression and metastasis in vivo and in vitro." (PMID 30588744, 2019). "Moreover, the average tumor weight was distinctly lower in the sh-LUCAT1 group compared with the control group." (PMID 28423699, 2017). "In the mouse models of NSCLC, LUCAT1 knockdown could suppress tumor growth in vivo." (PMID 39930621, 2025). "However, it remains unclear whether LUCAT1, especially exosomal LUCAT1, participates in targeted drug resistance of tumor cells." (PMID 41145422, 2025). "To determine the clinical significance of LUCAT1, UCA1, and MIR31HG in HNC, we evaluated the associations of molecular expression with clinical presentations to assess their predictive power in diagnosis and prognosis using TCGA-HNSC data of the 43 HNC patients with paired normal and tumor samples." (PMID 36980216, 2023). "Furthermore, PTBP1 binds the 5′ UTR internal ribosome entry site in HIF1α mRNA, enhancing HIF1α translation, and accounts for 40–50% of hypoxia-stabilized HIF1α levels, increasing the influence of hypoxia-induced LUCAT1/PTBP1 complexing on tumour suppressor inactivation through alternative splicing." (PMID 32536347, 2020). "Mechanistic investigation disclosed that LUCAT1 plays a role in modulating the stability of DNMT1, leading to the inhibition of tumour suppressor gene expression via DNA methylation." (PMID 40387409, 2025). "Silencing LUCAT1 in KYSE‐30 cells by decreasing DNA methylation exhibited a decrease in cellular proliferation, initiation of apoptosis and upregulation of tumour‐suppressor genes." (PMID 40387409, 2025). "Second, while this study primarily focused on the LUCAT1/c-MET axis, tumor drug resistance is generally the result of multifactorial and multi-pathway interactions." (PMID 41145422, 2025). "Biological roles of LUCAT1 were assessed through in vitro and in vivo experiments, including immunoblotting, RNA immunoprecipitation (RIP)-qPCR, xenograft tumor models, and organoid models." (PMID 41145422, 2025). "Future research should further investigate whether LUCAT1 interacts with other known osimertinib resistance mechanisms (such as bypass activation and histological transformation), as well as its potential role in tumor microenvironment remodeling (e.g., immune suppression)." (PMID 41145422, 2025). "These assays revealed a positive correlation between LUCAT1 and HMGA1 in BC, and this correlation was verified in clinical BC tumour samples." (PMID 40025525, 2025). "Two lncRNAs (CASC9 and LUCAT1) were shown to be upregulated and one (LINC01093) downregulated in tumor tissues." (PMID 38398157, 2024). "We found that LUCAT1 and AL031985.3 exhibited higher expression levels in tumor tissues compared to normal liver tissues, while AC015908.3 showed lower expression in tumor tissues compared to normal liver tissues." (PMID 37945918, 2023). "Five oncogenic (LUCAT1, MIR31HG, UCA1, HIF1A-AS2, and SUMO1P3) and tumor-suppressive (LINC00312) lncRNAs were independently validated, and three key molecules were further examined." (PMID 36980216, 2023). "It was found that both LUCAT1 and AL031985.3 were upregulated in tumor tissues compared to normal tissues (p values < 0.05 for both), while AC015908.3 exhibited higher expression in normal liver tissues and lower expression in tumor tissues (p < 0.04)." (PMID 37945918, 2023).